FOXP3 (forkhead box P3)
Diseases named in the same sentence as FOXP3 in open-access papers (continued):
Sharing a sentence is not in itself a finding about the gene and the disease.
Arthritis (110 papers, 2009 to 2025). Inflammation of a joint. "Together, these data indicated that increase in FoxP3-expressing Treg cells, accompanied by decrease in Th1 and Th17 responses, was involved in the mechanisms underlying arthritis remission under SM-MSC treatment." (PMID 28751919, 2017). "Intriguingly, their proportions relative to CD25+FOXP3+ Tregs associate with arthritis course, suggesting a role in disease." (PMID 26561546, 2015). "Protection from arthritis was associated with an increased ratio of Foxp3, and decreased IL-17 producing T cells in the synovia." (PMID 20479941, 2010). "The co-administration of heptanoyl CoA (a competitive inhibitor of butyrate synthase) confirmed the contribution of madecassoside-induced butyrate to the anti-arthritis action, as it caused the downregulation of ileum Treg cell number and expression of Foxp3 and IL-10." (PMID 37511889, 2023). "Additionally, earlier onset of disease and more aggressive disease progression were observed in the K/BxN model of spontaneous arthritis in scurfy mice, a mouse strain that is devoid of Treg cells due to a mutation in the Foxp3 gene and, consequently, develops severe multiorgan inflammation." (PMID 26314565, 2016). "Insome situations, it can also promote cell differentiation and proliferation,reducing the function of regulatory T (Treg) cells in patients withrheumatoid arthritis by dephosphorylating FOXP3." (PMID 40047620, 2025). "The results indicated that the mice received FoxP3+Bcl-xL-transduced Tregs showed a lower arthritis score than FoxP3 alone group." (PMID 38720903, 2024). "It modulates chronic inflammatory responses in different forms of arthritis by regulating Foxp3 expression in regulatory T cells and STAT6 in B cells." (PMID 39161423, 2024). "Sustained miR-34a expression in CD4+ T cells from RA patients or arthritis mouse models influences cellular Foxp3 expression, altering Treg cell polarization/generation and aggravating RA progression." (PMID 35625530, 2022). "IL-6 is among the main factors converting FoxP3+ Treg cells to the Th17 phenotype and is often found in high concentration in the synovium of patients with arthritis." (PMID 36389710, 2022). "In a rat arthritis model, HSP60 administration showed increased number of Treg cells (CD4+, FoxP3+) in the joint‐draining lymph nodes and improved arthritis symptoms." (PMID 35928554, 2022). "Th1 cells and Th17 cells regarded as arthritogenic and autoreactive immunocytes which predominately promoted the inflammatory responses, while the Foxp3-expressing Treg cells exhibited an essential suppressive role on the development of arthritis." (PMID 34079556, 2021). "IGFBP4 (144 ng), with IGFBP6 (85 ng) and 3 (10 ng), was shown to balance the IGF-dependent induction of CD4+FOXP3+ Tregs given by MSC-conditioned medium in arthritis." (PMID 32345351, 2020). "The frequencies of CD4+CD25+FoxP3+ Tregs in blood, spleen and lymph nodes of mice with S. aureus arthritis, from day 3 to 14 after bacterial inoculation, were higher than those in healthy control mice." (PMID 32111171, 2020). "In the experimental groups that developed arthritis, Foxp3 expression correlated with Tbx21, indicating Treg polarization towards Th1." (PMID 33193352, 2020). "In contrast, Th2 (CD4+IL-4+) and Treg cells (CD4+Foxp3+), known to play critical roles counteracting inflammation in arthritis, were increased only in the late stages of arthritis 19,21." (PMID 32332732, 2020). "Kirenol is a characteristic chemical constituent of SG that decreases the collagen-induced inflammation of arthritis joints through the regulation of the balance of T cells and cytokine levels via the NF-κB, Foxp3, and nuclear annexin-1 pathways." (PMID 31572487, 2019). "Mice treated with acarbose prior to arthritis induction had significantly increased CD4+CD25+Foxp3+ Treg cells as well as elevation of Helios and CCR6 as demonstrated in both percentage and absolute Treg cell numbers." (PMID 32116681, 2019).
Arthritis (continued). "This study demonstrates that VD treatment significantly delayed CIA disease onset and decreased the severity of arthritis by downregulating inflammatory Th17 cells while increasing CD4+Foxp3+Nrp-1+ cells." (PMID 30792721, 2019). "In the present study, we demonstrated for the first time that IL-18-expressing plasmid gene combined with IL-4 skewed the balance of Th1/Th2/Th17 to a Th2 type and increased GATA-3 and Foxp3 expression on collagen-induced arthritis." (PMID 29854762, 2018). "Schistosoma mansoni and T. spiralis derived antigens have been demonstrated to exert protective effect against adjuvant arthritis by upregulation of the Foxp3+ Tregs." (PMID 30093899, 2018). "In the case of murine arthritis, naïve CD4+ T-cells were engineered to co-express FOXP3 with HLA-DR1, covalently linked to an immunodominant peptide capable of driving collagen-induced arthritis." (PMID 29503652, 2018). "In this review, we discuss the role of Foxp3 dynamics in the control of T-cell responses in childhood arthritis, by reviewing evidence in humans and relevant mouse models of inflammatory disease." (PMID 30333832, 2018). "To our knowledge, this is the first study using the Foxp3-DTR-eGFP mouse on a C57BL/6 background for Treg depletion in an arthritis model, and we here demonstrate the usefulness of the approach to study the role of Tregs and IL-17 in arthritis." (PMID 26822477, 2016). "As a result, Foxp3-infected B cells delayed the onset of arthritis and suppressed its severity in CIA mice." (PMID 27350539, 2016). "Mice receiving Foxp3-tranfected B cells had a lower clinical score of the affected arthritic joints and a delay in the development of arthritis compared to the CIA mice." (PMID 27350539, 2016). "Analysis of Foxp3 mRNA showed a significantly higher Foxp3 expression in paws on day 3 and 8 compared to before arthritis induction." (PMID 26822477, 2016). "In order to assess the importance of Tregs in regulating DTHA severity, we selectively depleted Tregs by administration of DT at 24 and 48 h after arthritis induction to Foxp3-DTR-eGFP mice (FoxP3-DTR+) and littermate controls (FoxP3-DTR−)." (PMID 26822477, 2016). "It has already been shown that bovine milk exosomes increased Foxp3 expression and attenuated arthritis in two mouse models." (PMID 27175277, 2016). "In arthritis, the beneficial effect of gingival derived MSC is associated with an increased frequency of CD4+CD39+Foxp3+ Treg cells and an inhibition on Th1 and Th17 lineages." (PMID 27847522, 2016). "We observed that the Foxp3+ B cells showed a strong suppressive effect against arthritis in CIA mice." (PMID 27350539, 2016). "In a mouse model of collagen-induced arthritis, low doses of DCs showed excellent anti-arthritis activity by induction of Foxp3+ Tregs, whereas high numbers accelerated arthritis symptoms." (PMID 26617604, 2015). "Previously, we have shown that administration of Hsp70 or Hsp70-derived peptides suppresses experimental arthritis via the activation of CD4+CD25+FoxP3+ Tregs." (PMID 26107957, 2015). "An important caveat for the interpretation of our arthritis and atherosclerosis data is that Foxp3 has been shown to be expressed in epithelial cells of breast, lung, prostate and intestinal tissue." (PMID 25770018, 2015). "This population represents a Treg subset that has very low FOXP3 expression, is proportionally increased in the more severe forms of arthritis, and displays defects in pathways important for Treg homeostasis." (PMID 25092890, 2014). "The therapeutic induction of Foxp3+ Treg cells can then protect from inflammatory pathology such as arthritis or neuro-inflammation." (PMID 23324136, 2013). "We found that this approach only worked if the iFoxp3-transduced TH cells were exposed to arthritis antigens prior to switching on Foxp3." (PMID 22004905, 2012).
Arthritis (continued). "In that study, TLR2−/− mice had reduced FoxP3 expression, greater IL-17 expression, and increase arthritis severity, while TLR4−/− mice had a lesser severity of arthritis, and lowered IL-17 expression." (PMID 21695198, 2011). "In other diseases, like the arthritis mouse model, orally administered type II collagen was shown to induce CD4+CD25+Foxp3+ regulatory cells by IDO expressing CD11c+ DCs in intestinal Peyer's patches in the treatment of arthritis." (PMID 21765853, 2011). "The results of the present study demonstrate that FoxP3 and Bcl-xL can cooperatively promote the differentiation and persistence of Tregs, thereby resulting in prevention of arthritis." (PMID 20384988, 2010). "Mice receiving FoxP3-plus-Bcl-xL-transduced Tregs had a significantly decreased incidence of arthritis compared with mice receiving Tregs transduced with FoxP3 alone (32% versus 70% on day 60)." (PMID 20384988, 2010). "FoxP3 and Bcl-xL can cooperatively promote the differentiation and persistence of Tregs, with the capacity to prevent arthritis." (PMID 20384988, 2010). "In the present study, using the 2A sequence and a similar approach, we found that FoxP3 and Bcl-xL can also cooperatively promote differentiation and persistence of Tregs, resulting in the prevention of arthritis development." (PMID 20384988, 2010). "We assessed the Treg population based on their constitutive expression of the transcriptional factor Foxp3 in the blood, spleen, mesenteric and inguinal lymph nodes 4 and 26 days after arthritis induction." (PMID 19570235, 2009). "However, the FOXP3 mRNA expression in isolated CD4+CD25+CD127dim/− T cells tended to be higher in the arthritis patients than in the HCs, with the highest expression levels in isolated cells of RA and SpA patients." (PMID 40806470, 2025). "Results from NR4A1-KO mice indicate that inflammatory Ly6Chigh monocytes contribute to a mouse model of arthritis; in NR4A wild-type mice, CsnB increases levels of CD4+, CD25+, and FOXP3+ Treg cells in the presence of Ly6Clow monocytes to inhibit progression of arthritis." (PMID 40871737, 2025). "Arthritis protection in the high Mg diet was also associated with decreased expression of the pro-inflammatory cytokines TNFα, IL1β, and IL6 and increased numbers of IL10-producing Tr1 and Foxp3+ Treg cells." (PMID 39683640, 2024). "Furthermore, Haque retrovirally transduced murine iPSCs with specific TCR and FoxP3 and developed an Ag‐specific Treg with the ability to suppress autoimmunity in a murine model of arthritis." (PMID 36855955, 2023). "It was found that B29-induced CD4+CD25+Foxp3+ T cells could suppress arthritis in the proteoglycan-induced RA mice model both prophylactically and therapeutically, indicating these self-antigen-specific Treg cells could regulate immune disorder in vivo." (PMID 36248797, 2022). "Interestingly, the GFP-modified Foxp3 was protective in a model of arthritis due to disruption in HIF1α binding and increasing Foxp3 interactions with Interferon Regulatory Factor 4 (IRF4) leading to improved Treg control of Th2 and Th17 responses." (PMID 36032083, 2022). "In M1-polarizing conditions, 65–79*SE was predicted to stimulate activation of pro-inflammatory, pro-RA upstream regulators, such as Stat3, Rel, Rela, Jun, Ctnnb1 and Hif1a, among others, and to inhibit anti-arthritis or anti-inflammatory regulators (e.g. Klf2, Xbp1, Foxp3)." (PMID 33510427, 2021). "Similarly, oral administration of triterpenoid saponin, madecassoside provided anti-arthritis effects through enhanced secretion of IL-10 from the small intestine of collagen induced arthritis rats and the accumulation of Foxp3+ cells in the lamina propria." (PMID 34479568, 2021). "It was subsequently suggested that madecassoside may exhibits anti-arthritis potency through affecting the secretion of IL-10 from Foxp3+ cells in lamina propria of intestine, thus regulates the immune function of rats with collagen-induced arthritis." (PMID 33013406, 2020).
Arthritis (continued). "As others have found, we show here a physiological increase in the frequency of CD4+CD25+FoxP3+ Tregs in blood, spleen and lymph nodes during the natural course of S. aureus arthritis, which is most likely due to the host’s regulation of the evoked immune response." (PMID 32111171, 2020). "Moreover, it has been described that under certain conditions of experimental arthritis a subpopulation of Foxp3+ Treg cells can convert into autoreactive Foxp3− TH17 cells." (PMID 31551927, 2019). "The results demonstrated that spleen tissues from arthritis mice treated with A77 1726 showed dose-dependent increases in the number of Foxp3+ Treg cells and reciprocal decreases in the number of Th17 cells compared with spleen tissues from mice treated with vehicle." (PMID 28193225, 2017). "Several animal studies for example demonstrated that ectopic expression of Foxp3 in conventional T-cells by retroviral gene transfer resulted in a Treg-like phenotype and function and that these Foxp3-transduced T-cells were able to suppress arthritis in a murine host." (PMID 28098832, 2017). "To our knowledge, this is the first study using the Foxp3-DTR-eGFP mouse on a C57BL/6 (B6) background for Treg depletion in an arthritis model, and we here demonstrate the usefulness of the approach and build upon the already existing body of work in this new model." (PMID 26822477, 2016). "Treg depletion in Foxp3-DTR-eGFP mice on a DBA/1 background exacerbated G6PI-induced arthritis." (PMID 26822477, 2016). "In our study, the existence of Foxp3+ Bregs was demonstrated in mice arthritis model." (PMID 27350539, 2016). "Foxp3+ B cells successfully suppress arthritis and induced the Treg cell population." (PMID 27350539, 2016). "We have described in the present study that stable FOXP3 expression is decoupled from TSDR demethylation in a population of joint-infiltrating Tregs in human arthritis, and that the proportional representation of such cells within the Treg subset correlates with disease severity." (PMID 25092890, 2014). "Two recent reports, however, suggest that this modification of FoxP3 may alter its function in models of autoimmune diabetes or arthritis." (PMID 23593464, 2013). "The results showed a larger population of Foxp3+ Treg cells in GSPE-treated arthritis mice." (PMID 24223854, 2013). "Our data suggests that protection from arthritis induced with anti-CD4 is associated with an overall decrease of infiltrating T cells in synovial tissue and, within those T cells in the synovium, with an increase in the frequency of synovial Foxp3+ Treg cells." (PMID 20479941, 2010). "Given that IL-17-expressing CD4+ T helper 17 (Th17) cells and FOXP3+CD4+ regulatory T (Treg) cells play critical roles in the pathogenesis of both periodontitis and arthritis, we examined whether the R878H mutation affects the differentiation of naive T cells to Th17 or Tregs." (PMID 38838669, 2024). "It was proved, that under arthritis conditions CD4+CD25loFoxp3+ cells may lose Foxp3 expression and undergo trans-differentiation into Th17 cells, that accumulate in inflamed joints and participate in the pathogenesis of autoimmune arthritis which was shown on mice and human cells." (PMID 32111105, 2020). "Therefore, we tested whether Foxp3-transfected CD19+ B cells could ameliorate the development of arthritis in a CIA model." (PMID 27350539, 2016). "In the present study, we investigated the existence of Foxp3-expressing B cells, and their regulatory roles in mice arthritis model, by testing whether they could regulate the proliferation of effector T cells in vitro through a cell-to-cell contact-dependent mechanism." (PMID 27350539, 2016). "The high Mg2800 diet reduced arthritis severity and joint damage and reduced synovial inflammation and the expression of cytokines while increasing the numbers of CD4+Foxp3+ Treg cells and IL10-producing Tr1 cells." (PMID 39683640, 2024).
Arthritis (continued). "We found that C21 raises the numbers of CD4+CD25+FoxP3+ T cells in CIA, a fact that likely contributed to the improvement of arthritis." (PMID 35874732, 2022). "Joint swelling and the arthritis-related expression levels of IL-1β, IL-6, RANKL, MMP9, and OC-Stamp were strongly reduced, while Foxp3 was induced." (PMID 36003376, 2022). "The mechanisms by which 20S(OH)D3 downregulates arthritis severity in the CIA model is likely related to reduction in CD4+ T cells, CD19+ B cells, anti-CII antibodies, and maintenance of CD4+CD24+FoxP3+Tregs." (PMID 34276665, 2021). "The analysis of T cell populations revealed that arthritis induction increased the number of RORγt+CD4+ T cells, whereas Foxp3+CD4+ T cells and to a lower extent Foxp3+CD8+ T cells were reduced in arthritic controls when compared with naïve mice." (PMID 31394717, 2019). "Our findings indicate that pIL-18 gene combined with IL-4 ameliorates arthritis in the CIA mouse by suppression of Th1 and Th17 cytokines and increasing expression of FoxP3 and GATA-3." (PMID 29854762, 2018). "IL administration of eASCs attenuated the severity and progression of arthritis, reduced bone destruction and increased the levels of regulatory T cells (CD25+Foxp3+CD4+ cells) and Tr1 cells (IL10+CD4+), in spleen and draining lymph nodes." (PMID 28484460, 2017). "Effects of sSiglec-9 were evaluated using a physiologic arthritis score, histological analysis, serum tumor necrosis factor (TNF)-α concentration, and the proportion of forkhead box P3 (Foxp3)-positive regulatory T (Treg) cells." (PMID 27267914, 2016). "VIP contributes to the generation of Foxp3 expressing IL-10 and TGF-β producing Tregs in severe inflammatory situation like arthritis." (PMID 27022966, 2016). "Although the Treg community has taken as a rule of thumb that stable FOXP3 expression is essential to Treg lineage stability, our data investigating the TCR repertoires in human arthritis suggest a more nuanced situation." (PMID 26561546, 2015). "At 25 days following the onset of arthritis, the percent frequencies of Th17 (CD4+IL-17+) and Treg (CD4+Foxp3+) cells among CD4+T cells isolated from the spleen of CIA mice treated with or without CD11b+DCs were determined." (PMID 25405209, 2014). "Thus, we determined the percent frequency of Th17 (CD4+IL-17+) and Treg (CD4+Foxp3+) cells in CD4+ T cells isolated from the spleen or the inguinal lymph nodes of CIA mice that were treated with or without varying modified allo-tDCs on day 21 following the onset of arthritis." (PMID 24204938, 2013). "We found significant increase in the ratio of CD4 + CD25 + Foxp3+ cells among CD4+ cells in TSA-treated group compared to control group, suggesting that Treg are involved in the prevention of arthritis in SKG mice with TSA." (PMID 21592365, 2011). "In the future, our focus will be directed towards elucidating the underlying mechanism by which PI16 influences the expression of Foxp3, while also exploring the potential correlation between levels of regulatory T cells (Tregs) and PI16 in patients suffering from enteritis and arthritis." (PMID 38566233, 2024). "A recent study has shown that oral co-administration of HSP 65 and L. lactis in CIA mouse model ameliorated clinical and histological signs of arthritis, reduced inflammatory cytokines (IFN-γ and IL-17), as well as increased CD4+Foxp3+Tregs and CD4+LAP+ T cells." (PMID 36248797, 2022). "Further, kaempferol could effectively improve the symptoms of arthritis in mice and decrease the PIM1-mediated phosphorylation of S422 at Foxp3." (PMID 36248435, 2022). "Since arthritis in mice with CIA results from a contribution by CD4+ T cells and B cells which may be suppressed by CD4+CD25+Foxp3+ Tregs, it was important to determine whether percentages of these cell populations were changed by 20S(OH)D3 treatment." (PMID 34276665, 2021).